AFP (alpha fetoprotein)
Diseases named in the same sentence as AFP in open-access papers (continued):
Sharing a sentence is not in itself a finding about the gene and the disease.
liver cancer (continued). "In current study, TAP was shown positively correlated with the established marker AFP in liver cancer, confirming its potential role as a promising indicator." (PMID 32176062, 2020). "At week 6 after the initial paOAd infection, the human AFP (a specific liver cancer marker)-positive cells were almost disappeared." (PMID 32703933, 2020). "We compared the expression of the coding genes of AFP, CEA and PSA, and found that only AFP expression correlated with its serum levels in liver cancer patients." (PMID 31897235, 2020). "AFP has been used as tumor marker to help detect cancer of the liver and plays important role in the early diagnosis." (PMID 32176062, 2020). "Survival analysis indicated high serum AFP levels was prognostic of poorer survival of the liver cancer patients (Log-rank test: p = 0.046)." (PMID 31897235, 2020). "The distribution of liver cancer samples was plotted using the top three principal components and patients are colored by their serum AFP levels." (PMID 31897235, 2020). "Similar to the findings in liver cancer, fetal liver showed high methylation in cg10778295 and lower expression of AFP (t = 5.56, P = 0.01; t = -6.91, P = 0.02)." (PMID 31897235, 2020). "Alpha-fetoprotein levels and visual analogue scale levels significantly decreased after treatment compared with the baseline levels in patients with primary liver cancer (p<0.05)." (PMID 33194582, 2020). "Methylation analysis revealed de-methylation of AFP promoter occurred in some liver cancer tissues, and was significantly related to AFP mRNA expression." (PMID 31897235, 2020). "In liver cancer patients, serum AFP levels correlated significantly with AFP mRNA expression in cancer tissues (r = 0.72, p = 1.6e-45)." (PMID 31897235, 2020). "AFP expression mainly occurs in fetal liver cells, and although AFP disappears from the blood about 2 weeks after birth, its overexpression can be detected in liver cancer patients." (PMID 33072587, 2020). "Survival analysis indicated poorer survival in liver cancer patient with middle and high serum AFP levels (Log-rank test: P = 0.046)." (PMID 31897235, 2020). "Apart from liver cancer, high expression of AFP was also observed in breast cancer (BRCA), gastric cancer (STAD) and lung cancer (LUAD, LUSC) sometimes." (PMID 31897235, 2020). "To further assess the potential, we compared with the established cancer markers, for example, AFP in liver cancer and CA19-9 in pancreatic cancer." (PMID 32176062, 2020). "Our data revealed that de-methylation of a CpG locus in the AFP promoter occurred in some liver cancer tissues, and was significantly related to AFP mRNA expression." (PMID 31897235, 2020). "To identify key genomic modules co-regulated with AFP, we performed gene co-expression analysis using mRNA sequencing data of liver cancer." (PMID 31897235, 2020). "MUC-1 (CA15-3/CA27.29) and plasminogen activator inhibitor (PAI-1) have been reported as biomarkers for beta-human chorionic gonadotropin (Beta-hCG); breast cancer; testicular cancer; alpha-fetoprotein (AFP) for liver cancer and germ cell tumors." (PMID 33302373, 2020). "A large number of studies have shown that GPC3 is more sensitive than AFP in the diagnosis of liver cancer." (PMID 32127929, 2020). "Alpha-fetoprotein (AFP) is the most commonly used marker for the diagnosis and prognosis of liver cancer and HB." (PMID 32758256, 2020). "Our findings suggest that AFP can serve as a potential target in the development of therapeutics for liver cancer." (PMID 33009373, 2020). "In liver cancer, a strong correlation between AFP gene expression and serum levels was observed (r = 0.72, p = 1.6e-45)." (PMID 31897235, 2020). "AUC-ROC analysis also indicated that the combination of RRM2 with AFP to diagnose liver cancer (AUC: 0.947, 95% CI 0.919–0.974) was even better than either AFP or RRM2 alone, with a sensitivity of 88.7% and a specificity of 97.0%." (PMID 33372599, 2020).
liver cancer (continued). "Liver cancer screening in the clinic is typically based on the detection of serum alpha-fetoprotein and various imaging methods." (PMID 32536814, 2020). "In another dataset GSE14520, liver cancer patients with high and low serum AFP were also clearly separable as indicated by PCA analysis." (PMID 31897235, 2020). "To further assess the implications of high expression of AFP in liver cancer, we performed a thorough correlation study between serum AFP and clinicopathological features of the patients from TCGA study." (PMID 31897235, 2020). "Immuno-reactive liver cancer markers AFP, GPC3 and CK19 were positively stained as well as the CSC markers such as CD44, CD24 and CD133 in the tumour tissue developed in the liver." (PMID 32203212, 2020). "From hepatitis to liver fibrosis, liver cirrhosis and liver cancer are long and difficult to find process, and even if the alpha‐fetoprotein (AFP) detection abnormalities, but the imaging confirmation takes months or longer." (PMID 30341783, 2019). "It outweighs the traditional alpha-fetoprotein (AFP) kit in being capable of identifying AFP-negative liver cancers from just 0.2 ml blood plasma with 84% sensitivity and 88% specificity." (PMID 31608229, 2019). "The sensitivity of GP73 for detection of liver cancer was 74.6%, and specificity was 97.4%, while the sensitivity of AFP for detection of liver cancer was 58.2% and specificity was 85.35%." (PMID 30341783, 2019). "We examined the liver cancer stem cell or progenitor markers (AFP, CD133, EPCAM, and KRT19), and hepatocyte terminal differentiation markers (ALB, G6PC, CYP3A4, and HNF4A) in subgroup of patients with different SOX signature scores." (PMID 31462277, 2019). "Many studies on cantilever-based biochemical detection have been reported, and high sensitivity and low detection limits for protein detection such as early liver cancer markers alpha fetoprotein (AFP) and hepatocyte growth factor (HGF) have been achieved." (PMID 31362399, 2019). "Even serum AFP, which is regarded as the “gold standard” biomarker for liver cancer, is also used as a biomarker of testicular cancer accompanying with human chorionic gonadotropin (HCG), based on their highly-elevated expression in testicular cancer patients." (PMID 31363116, 2019). "Serum alpha-fetoprotein (AFP) screening has become a routine clinical practice to diagnosis early stage liver cancer and monitoring recurrence in many parts of the developed world." (PMID 31165038, 2019). "For example, α-fetoprotein (AFP) has been developed as a biomarker for the early diagnosis of liver cancer." (PMID 30935114, 2019). "HOXC6 overexpression correlated with high AFP level (P = 0.038), liver cirrhosis (P = 0.044), larger tumor (P = 0.001), vascular invasion (P = 0.046) and Barcelona Clinic Liver Cancer (BCLC) stage (P = 0.005)." (PMID 29348394, 2018). "The prognostic value of PFS and OS-pPET-RadScore, Barcelona-Clinic Liver Cancer staging system and serum alpha-fetoprotein level was analyzed to predict PFS and OS in multivariate analysis." (PMID 29435123, 2018). "Another sensing scheme has been presented recently for the determination of alpha-fetoprotein (AFP), which can serve as a marker of liver cancer." (PMID 30513775, 2018). "The early detection rate of 23.5% (4 of 17) among HBsAg-positive liver cancer patients who had elevated AFP is similar to the rate of 23.1% (6 of 26) among HBsAg-positive patients who were AFP negative." (PMID 30143694, 2018). "These limitations preclude a firm conclusion that screening with AFP and ultrasonography examination in an HBsAg-positive population can reduce liver cancer mortality." (PMID 30143694, 2018). "AFP is a diagnostic and prognostic HCC marker for more than 70% of primary liver cancers, and is clinically employed to grade the progression of HCC." (PMID 35539339, 2018).
liver cancer (continued). "For example, a recent report demonstrated that a novel CAR can selectively and specifically target the cell surface complex of the specific liver cancer marker alpha-fetoprotein (AFP) derived AFP158–166 peptide and HLA-A*02:01." (PMID 29448937, 2018). "AFP has been commonly used for clinical early diagnosis of liver cancer despite limited sensitivity and specificity." (PMID 30220970, 2018). "Currently α-fetoprotein (AFP) combining with pathological detection are commonly used in the early diagnosis of liver cancer." (PMID 30220970, 2018). "AFP has served as a classical biomarker of liver cancer since the 1970s but is now recognized as a key signalling molecule involved in several aspects of tumour biology." (PMID 30301886, 2018). "For decades, AFP has been considered as a gold standard in the diagnosis of liver cancer with high reliability based on long accumulated clinical experiences, even though its diagnostic sensitivity to HCC is low at about 50%." (PMID 29954402, 2018). "For example liver cancer cell lines show different phenotypes in terms of liver marker expression like AFP and/or their epithelial or mesenchymal characteristics which need to be tested in vivo for their tumor forming and metastatic potentials." (PMID 29371671, 2018). "Currently, the clinical diagnosis of liver cancer mainly depends on imaging and serum markers such as AFP." (PMID 30065664, 2018). "Where, alpha fetoprotein (AFP) a HepG2 specific protein, has been regarded as one of the key chemoattractants for S. typhimurium to target liver cancer cells." (PMID 29686328, 2018). "The testing results of two kinds of liver cancer biomarker AFP and GGT-II show agreement between experiment and simulation." (PMID 29180650, 2017). "The main objective of this study is to evaluate the antitumour property of ChV in liver cancer- induced rats, by determining the level and expression of novel tumour marker AFP, and comparing with other possible markers M2-PK, OV-6 and TGF-β." (PMID 29268718, 2017). "Alpha-fetoprotein (AFP) is considered a vital and mature biomarker in the diagnosis of liver cancer, especially in the case of LIHC." (PMID 28316892, 2017). "Elevated BARD1 expression was positively correlated with tumor-node-metastasis stage, Barcelona-Clinic Liver Cancer stage, hepatitis B surface antigen, large tumor size, serum alpha-fetoprotein levels, and serum aspartate aminotransferase levels." (PMID 28794477, 2017). "Genes specifically expressed in liver cells [i.e., albumin (ALB) and tyrosine aminotransferase (TAT)] and a gene expressed in liver cancer/immature cells [i.e., α-fetoprotein (AFP)] were used as endogenous control genes." (PMID 29065189, 2017). "Liver cancer rats treated with 300 mg/kg ChV resulted in suppression of the proteins, as evidenced by the smaller amount of brown-stained cells for AFP, OV-6, M2-PK and TGF-β." (PMID 29268718, 2017). "Serums levels of PIVKA-II and a-Fetoprotein (AFP) was detected and compared in 113 patients with clinical confirmed Barcelona Clinic Liver Cancer (BCLC) stage 0-A HBV-related HCC and 161 chronic hepatitis B (CHB) patients." (PMID 28852419, 2017). "Diagnostic markers are used to aid in diagnosis and recurrence screening; typical examples include prostate-specific antigen in prostate cancer and alpha-fetoprotein in liver cancer." (PMID 29290942, 2017). "Currently, the most widely used biological marker of liver cancer is alpha fetoprotein (AFP), especially in developing countries." (PMID 28322348, 2017). "The AuNP-modified GC electrode was further modified with protein A and AFP antibody (anti-AFP) to prepare immunosensors for AFP, a biomarker for liver cancer." (PMID 28672780, 2017). "Fucosylated glycoproteins such as AFP (α-fetoprotein) and CA 19-9, are used as tumor biomarkers of pancreatic and liver cancers, and new fucosylated glycoproteins have been found to serve as markers for small cell lung cancer." (PMID 28763000, 2017).
liver cancer (continued). "One study evaluated combination of biannual testing of serum alpha fetoprotein and liver ultrasonography to screen for liver cancer and reported that the proportion of liver cancers detected at an early stage was 90%." (PMID 29250323, 2017). "AFP DNA was chosen in this study because it is unique in liver cancer and was considered as highly needed by the cells." (PMID 28109303, 2017). "For liver cancer screening, an alpha-fetoprotein test and sonography are recommended, and for colorectal cancer, a yearly fecal occult blood test in combination with colonoscopy or a double-contrast enema in the case of abnormal findings is recommended." (PMID 28793755, 2017). "In the univariate analysis, serum alpha-fetoprotein (AFP) level, tumor-nodes-metastases (TNM) stage, and Barcelona Clinic Liver Cancer (BCLC) stage were revealed to significantly associated with OS and TTR of HCC patients." (PMID 28874807, 2017). "Our earlier study has shown the development of liver cancer nodules and increased serum AFP in rats fed with CDE diet." (PMID 29268718, 2017). "A univariate Cox regression model indicated that 6 variables including AFP, Barcelona Clinic Liver Cancer stage (BCLC stage), tumor rize, vascular invasion, miR-192-5p and miR-29a-3p were correlated with the survival of HCCs." (PMID 27317768, 2016). "The identification of alpha-fetoprotein (AFP) is interesting because for decades it has been the most widely used biochemical blood test for liver cancer." (PMID 26808496, 2016). "ICC accounts for approximately 5% of primary liver cancers and AFP positive ICC accounts for less than 1%." (PMID 27835609, 2016). "Compared with AFP generated by benign hepatic diseases, AFP generated by hepatic cancer has a much higher fucosylation index." (PMID 27528397, 2016). "In this study, we elucidated that high serum concentration of AFP was positively associated with metastasis of HCC cells in clinical patients, and found that AFP harbours a function to promote metastasis of liver cancer cells in vitro and in vivo." (PMID 26756858, 2016). "These proteins include cancer antigen 125 (CA125) in ovarian cancer, alpha-fetoprotein (AFP) in liver cancer, carcinoembryonic antigen (CEA) in colon cancer, and prostate-specific antigen (PSA) in prostate cancer." (PMID 27863386, 2016). "Forty‐seven clinical patients' liver samples were collected and diagnosed; HCC cells line, Bel 7402 cells (AFP‐producing) and liver cancer cell line cells (non‐AFP‐producing) were selected to analyse the role of AFP in the metastasis of HCC cells." (PMID 26756858, 2016). "Currently, α-fetoprotein (AFP) together with pathology and iconography detection are routinely used in early clinical diagnosis for liver cancer." (PMID 27565572, 2016). "Over the past few decades, professor Mengsen Li with his partners have been addressing the connection between AFP and liver cancer cell growth, apoptosis and drug resistance." (PMID 27835609, 2016). "Some researchers have studied the effects of AFP on liver cancer cell growth, migration, and apoptosis." (PMID 27835609, 2016). "Many results demonstrated that GP73 is an excellent marker for HCC diagnosis, and its sensitivity and specificity are better compared with the common liver cancer marker α fetoprotein (AFP), which reach 75% and 97% separately, while 58% and 85% for AFP." (PMID 25980438, 2015). "For instance, alpha fetoprotein (AFP) is widely used as one facet in the process of diagnosing liver cancer." (PMID 25710884, 2015). "PLC/PRF/5 cells (AFP-producinger) and HLE cells (non AFP-producinger) were used to further examine the effect of AFP on CXCR4 expression in human liver cancer cell lines in the present study." (PMID 25815363, 2015). "For example, the relationship between carcinoembryonic antigen (CEA) and colorectal cancer and that between alpha-fetoprotein (AFP) and liver cancer, which have been successfully applied in clinical settings." (PMID 26076456, 2015).
liver cancer (continued). "Alpha-Fetoprotein (AFP) is by far the most commonly used serological biomarker in clinical practice for liver cancer screening, early diagnosis, evaluation of therapeutic efficacy and prognosis." (PMID 25826090, 2015). "Clinically, liver cancer can be screened for by using the α-fetoprotein (AFP) test and carcino-embryonic antigen (CEA) test." (PMID 26610504, 2015). "AFP is by far the most commonly used serological biomarker in clinical practice for liver cancer screening, early diagnosis, evaluation of therapeutic efficacy and prognosis." (PMID 25826090, 2015). "High expression of SPC24 was significantly correlated with alpha-fetoprotein (AFP) (p = 0.044), median size (p = 0.030), tumor number (p = 0.019), and Barcelona-Clinic Liver Cancer (BCLC) stage (p = 0.015)." (PMID 26515591, 2015). "Despite its low specificity for individual cancer types, AFP is the best-studied serological biomarker for HCC which is the most common type of liver cancer." (PMID 26509158, 2015). "The aim of this study is to elucidate the effectiveness and complications of fine needle aspiration in a Chinese population with primary liver cancer and AFP levels ≤200 ng/ml." (PMID 25170868, 2014). "Regarding liver cancer, some tumor characteristics have been shown to have prognostic value, including vascular invasion and an increased AFP level." (PMID 24788770, 2014). "The weak expression of XAF1 has been shown to be associated with portal vein tumor thrombi (PVTT), preoperative AFP level, tumor size, and recurrence of liver cancer." (PMID 24980821, 2014). "The AFP-L3 ratio provides information complementary to total AFP level that can be used for the early recognition of malignant liver tumors and during follow-up of patients after therapy." (PMID 24927126, 2014). "The most downregulated gene was ZHX2 (-8.4 fold), which was shown to promote AFP secretion leading to activation in liver cancer." (PMID 26085845, 2014). "Studies have shown that this type of tumor is able to generate products, including albumin, α-antitrypsin, prothrombin, ferritin, transferrin and AFP, which are usually produced by normal liver cells and liver cancer cells." (PMID 24959228, 2014). "This selection period included patients with a suspected diagnosis of primary liver cancer whose AFP levels were ≤200 ng/ml and who underwent US-FNA." (PMID 25170868, 2014). "HepG2 represents a liver cancer cell line with positive alpha-fetoprotein expression, while PLC-PRF and SK-HEP-1 are typical cell lines negative for this protein." (PMID 25558904, 2014). "We also explored the possibility of the quantitative detection of a liver cancer tumor marker, α-fetoprotein (AFP), and performed a series of electrical experiments under various concentrations of AFP in human serum using the Fab-immobilized FET." (PMID 28788579, 2014). "For example, using this technique, Lens culinaris (LCH)-affinitive alpha-fetoprotein (AFP-L3) is separated, which is more accurate in diagnosing liver cancer than total AFP." (PMID 24428921, 2014). "AFP is overexpressed in human primary liver cancers and has been used broadly as a biomarker for HCC." (PMID 23951254, 2013). "α-fetoprotein (AFP) together with iconography and pathology detection are commonly used in the clinical early diagnosis of liver cancer." (PMID 24649215, 2013). "Animals treated with AFs showed a significant increase in AFP which is considered specific biomarkers for liver cancer." (PMID 24959547, 2013). "The program provides liver cancer screening (alpha-fetoprotein and ultrasonography) every 6 months for persons aged 40 or older who are positive for HBsAg, anti-HCV, or liver cirrhosis." (PMID 23672452, 2013). "AFP levels in normal adults are approximately 5–10 μg/L, which liver cancer patients usually exceed." (PMID 23717429, 2013).